CD4 (CD4 molecule)
Diseases named in the same sentence as CD4 in open-access papers (continued):
Sharing a sentence is not in itself a finding about the gene and the disease.
tumor (continued). "as CD4+CD25+ T cells that suppress an excessive immune response to various antigens but also contribute to tumor progression by inhibiting antitumor immunity." (PMID 40861448, 2025). "They provide the micromilieu to activate tumor antigen-specific CD4+ or CD8+ T cells and to promote B cell differentiation into plasma cells secreting tumor-reactive antibodies." (PMID 40282480, 2025). "The infiltration of a large number of CD4+ and CD8+ T cells in liver tissue was also associated with inhibition of tumor metastasis, which was consistent with the previous conclusions." (PMID 40498982, 2025). "The results demonstrated that the number of infiltrated CD4+ cells in tumor tissue was significantly increased (p < 0.05) following treatment with GSE, showing a 15.79% rise compared to the SEC group." (PMID 40843004, 2025). "CellChat analysis revealed that total CD4+ T cells, particularly cluster 2 cells, interacted with microglia, myeloid, tumor cells, and other CD45− cells, with increased numbers and strength of interactions noted in the M002-treated group." (PMID 39885128, 2025). "We used six other immune infiltration algorithms and found that the low-risk group had a richer infiltration of anti-tumor immune cells, such as CD8+ T cells, CD4+ T cells, active NK cells and B cells." (PMID 40703522, 2025). "Differential enrichment is observed not only at cancer cell type specific ATAC-seq peaks but also at CD4+ T cell specific peaks, suggesting both tumor- and immune-derived contributions to the cfDNA signal." (PMID 41225146, 2025). "Among these, CD4+ T cells, which are markers of helper T cells, are crucial for anti-tumor immunity." (PMID 40308586, 2025). "CD4+ aCEA-28ζ-sSF6 CAR T cells displayed a greater magnitude of CD25 upregulation upon co-culture with CEA+ BxPC-3 tumor cells in comparison to CD4+ aCEA-28ζ-GFP CAR T cells." (PMID 40558528, 2025). "CGB5-expressing tumor cells convert conventional CD4+ T cells into Tregs by up-regulating the immunosuppressive cytokines TGF-β and IL-10, together with the transcription factor FOXP3." (PMID 41048937, 2025). "Other investigators have also defined a pro-tumorigenic role of IFN-γ in tumors through a variety of mechanisms, including induced tumor stemness and increased CD4+ T cell apoptosis." (PMID 40553564, 2025). "For example, CD8+ T cells play an essential role in recognizing TAAs and mediating tumor cell killing, while CD4+ helper T cells participate in stimulating DC priming and activating CD8+ T cells." (PMID 40435257, 2025). "In the context of adoptive T-cell therapy, preclinical data have shown that CD4+ T-cell transfer can mediate tumor rejection." (PMID 40195474, 2025). "Multiplex immunofluorescence and immunohistochemistry showed key components of the tumor microenvironment, including relative proportions of CD4+ and CD8+ immune cell populations, were preserved." (PMID 40791544, 2025). "They observed a significantly higher distribution of CD8+ and CD4+ Tumour-Infiltrating Lymphocytes (TILs), which exhibit a small fraction of infiltrating CD4+ Foxp3+ Tregs indicating clinical effectiveness." (PMID 40852716, 2025). "In post-chemotherapy samples, tumor cell proportions were significantly reduced in the sensitive group, accompanied by decreases in CD4 T cells, CD8 T cells, and NKT cells." (PMID 40098624, 2025). "The most common cell types included luminal and luminal ER+ tumor, CD4 T cells, Vim+ fibroblasts, and quiescent stroma." (PMID 39808504, 2025). "To test these predictions, we examined the effects of conditioned medium (CM) obtained from mGSCs ± TGFBR2 inhibition on the viability and tumor cell-killing capacity of PBMC-derived CD4+ and CD8+ T cells." (PMID 40277917, 2025). "We then evaluated if CD4+ T cells contributed to the protection against tumor regrowth by re-challenging longer survivors in the M002-treated cohort at day 45 post-treatment through implanting GSC005 tumor cells in the contralateral hemisphere." (PMID 39885128, 2025).
tumor (continued). "Tumor cells can directly present tumor-derived peptides to CD4+ T helper lymphocytes when they have MHC-II molecules on them." (PMID 41018485, 2025). "Anti-VEGFA therapy can improve host adaptive tumor immune responses via vascular normalization, leading to increased tumor-infiltrating lymphocytes, such as CD4+ and CD8+ T cells." (PMID 40906526, 2025). "Collectively, these results suggest Pin1 inhibition reduces MSS CRC tumor growth through enhanced CD4+/CD8+ T cell accumulation and reduced Treg recruitment." (PMID 41246306, 2025). "Next, we completed DE analysis within CD4 T cells to compare expression profiles between tumor-infiltrating lymphocytes (TILs) and circulating lymphocytes." (PMID 39932553, 2025). "Increased NK cell function and reduced CD4+ cells leading to increased cytotoxic T-cell function have been postulated as one of the mechanisms by which Ra-223 kills tumor cells, beyond the reach of the alpha-radiation." (PMID 40978127, 2025). "In contrast, immune-activated or tumor-inhibited effectors, such as activated CD4 T cells, NK cells, plasma cells, M0, and M1 cells, were down-regulated." (PMID 40777025, 2025). "It has been shown that only a small number of CD4+ effector T cells (about 1% of tumor-infiltrating immune cells) are located at the tumor invasion edge, where they interact with CD11c+MHC-II+ antigen-presenting immune cells and indirectly eliminate tumors." (PMID 40458394, 2025). "This resulted in the egress of immunosuppressive gut-homing T cells (α4β7+CD4+ T cells) from the intestines to the tumor-draining lymph nodes, thereby facilitating tumor immune escape and diminishing the efficacy of ICI therapy." (PMID 41304278, 2025). "These alterations can reshape the tumor microenvironment by downregulating PD-L1 expression and reducing immune cell infiltration, particularly activated CD4 memory T cells, helper T cells, M1 macrophages, and NK cells." (PMID 41463229, 2025). "Our analysis revealed that HPV-positive tumors harbored more mature, tumor-proximal TLSs enriched with ICOS+ CD4+T- cells and CD45RO+T- cells, as well as CD21+ B- cells, supporting the presence of mature TLSs and active immune priming." (PMID 41254766, 2025). "Sustained vaccine-specific CD4+ and CD8+ T-cell responses were associated with durable tumor control, further supporting the long-term potential of personalized peptide vaccination." (PMID 41246310, 2025). "We examined CD4+Foxp3− Tconv and iTr35 in the spleen and blood by flow cytometry after sorting, CD4+Foxp3− Tconv expression was increased in tumor-bearing mice." (PMID 40259042, 2025). "RCOR2 was upregulated predominantly in tumor cells and promoted tumor development in mice through reducing tumor cell death by CD4+CD8+ T cells and inducing cancer stemness." (PMID 40608411, 2025). "To analyze PD-1 expression in MDV-transformed CD4+ T-cells, we compared the proportions of PD-1+ cells in the total CD4+ T-cells in the spleen and tumor tissues of chickens with MD." (PMID 40430752, 2025). "Increased Bifidobacterium abundance correlated with improved survival, while CD4+ T cell depletion led to gut dysbiosis and reduced anti-tumor effects in untreated mice." (PMID 40243570, 2025). "When the CD8+ cells increases, the ratio of the CD4+ and CD8+ cells changes, it can cause the immune function of the body to decrease, thereby weakening the anti-tumor ability of the body." (PMID 40787472, 2025). "Meanwhile, DHL/THL was predominantly enriched in the LME-DP category, while the tumor microenvironment in DHL-BCL6 showed a trend of elevated CD4 + and CD8 + T cell infiltration." (PMID 41364305, 2025). "To determine the impact of SCPs on immune cells in the tumor microenvironment, we analyzed the changes in CD4+ and CD8+ T lymphocytes in tumors of mice in the control and SCP groups using flow cytometry." (PMID 39941980, 2025). "In the tumor bed, we found a significant decrease in the percentage of CD4+Foxp3+GFP+ Tregs in mice depleted of CD8+ T cells." (PMID 40553564, 2025).
tumor (continued). "A recent study revealed TCF1+ stem-like CD4+ T cells in human kidney, bladder, and prostate tumors, highlighting their potential role in tumor immunity." (PMID 40634636, 2025). "CD8 + T cells and activated memory CD4 + T cells are the main executors of antitumor immune responses and can recognize and kill tumor cells." (PMID 40833956, 2025). "T cells, in particular, play a central role in anti-tumor immunity, with both CD8 and CD4 subsets contributing to immune surveillance and tumor eradication." (PMID 40076932, 2025). "A previous study demonstrated functional synergy of PD-1 and Lag3 in the control of anti-tumour immunity, and this was linked to increases in IFN-gamma-expressing cells amongst both CD4+ and CD8+ T cells." (PMID 40351814, 2025). "The Apo-A1 level in TTCS or arginase-1 expression in tumor-infiltrating neutrophils is negatively correlated with tumor-infiltrating CD4+ T population." (PMID 40358184, 2025). "The Meq+ CD4+ T-cells were detected in both the spleen and tumor tissues of infected chickens, and the proportion of Meq+ CD4+ T-cells was significantly higher in tumor tissues than in the spleens." (PMID 40430752, 2025). "Immune analysis demonstrated enhanced tumor infiltration of CD4+ and CD8+ T cells, initiated by TILT-123 and amplified by TIL infusion, while modulation of peripheral blood NK cell phenotypes further strengthened the immune response." (PMID 41024300, 2025). "Second, IHC analysis of CD4 and CD8α indicated that tumor-bearing mice typically had a greater number of these T cells in lymph nodes relative to their tumor-free counterparts." (PMID 41208884, 2025). "Downmodulation of CD6 in co-cultures with CD318+ tumor cell lines was also observed in CD4 and CD8+ T cells, and NK cells (CD56+)." (PMID 40391211, 2025). "Tumor size, Ki-67, Caspase-3, intratumoral infiltrated CD4+, CD8+ and FOXP3+ cells were detected immunohistochemically." (PMID 40843004, 2025). "When loaded with DTX, NPs further promoted immunogenic cell death, and enhanced antitumor immune responses as evidenced by the significant increase in tumor-infiltrating CD4+ and CD8+ T cell populations." (PMID 41471822, 2025). "Flow cytometry was employed to analyze immune cell populations, including tumor-associated macrophages (TAMs), myeloid-derived suppressor cells (MDSCs), regulatory T cells (Tregs), and cytotoxic T cells (CD8+ and CD4+)." (PMID 40094005, 2025). "This revealed that while the RP diet again suppressed tumor growth compared to the CL diet, depleting CD4+ and CD8+ T cells reversed that effect." (PMID 40105196, 2025). "In the present study, we monitored the dynamics of CD4+ T cells, including both uninfected cells and tumor cells." (PMID 40673706, 2025). "We also observed the infiltration of M1 macrophages in tumor tissues by immunohistochemistry, and detected the percentages of CD4, CD8 and other T cells subtypes in the peripheral blood and spleen tissues by flow cytometry." (PMID 40394236, 2025). "Among these, CD4+ T cells uniquely form a characteristic rosette-like arrangement around tumor cells." (PMID 41256864, 2025). "Within the tumor, naïve/central memory CD4 + T cells (9.4%), naïve B cells (9.1%), Tregs (7.8%), and tissue resident memory CD8 + T cells (7.1%) were the most abundant cell types, demonstrating a broad immune complement." (PMID 40848148, 2025). "In ascitic CD4+ T cells of tumor‐bearing mice, Tnfrsf14 knockdown resulted in a reciprocal increase in IFNγ‐producing Th1 cells and a decrease in IL4‐producing Th2 cells, whereas the levels of IL17‐producing Th17 cells remained similar." (PMID 40105652, 2025). "Taken together, our results suggest that M002 treatment reprogrammed the TME and expanded tumor-infiltrating CD4+ T cells with enhanced anti-tumor activity." (PMID 39885128, 2025).
tumor (continued). "The vaccine can target up to 20 predicted individual tumor neoantigens, increasing the number of antigen-specific T cells, such as induced CD4+ and CD8+ T cells targeting 58 (60%) and 15 (16%) of 97 unique neoantigens, respectively." (PMID 40733649, 2025). "CD4+ and CD8+ T cell exposure to tumor-associated succinic acid inhibits degranulation and cytokine secretion, thereby suppressing their antitumor effects." (PMID 40696413, 2025). "Compared with those in the NC group, the proportions of M0 macrophages and CD4+ T cells in tumor tissues changed slightly after the knockdown ofTREM1, while the proportion of M1 macrophages increased significantly." (PMID 40551711, 2025). "These tumor vaccines are taken up by APCs via different components and are delivered to CD8+ T-cells and CD4+ T-cells via MHCI and MHCII molecules, thus causing the activation of effector T-cells." (PMID 39911383, 2025). "We demonstrate that the antibody Fc effector function and CD4+ T cells are both required for the remodeling of tumor blood vessels and the increase of TA-HEVs during anti-CTLA-4 therapy." (PMID 40460830, 2025). "DRP/Res/siP significantly increased the infiltration of CD8+ T cells and CD4+ T cells in the tumor and raised the secretion level of IFN-γ." (PMID 40286130, 2025). "An overview of the immune cell profiles across seven tumor samples further confirmed consistent F4/80 and CD4 signals, with PD-1 and FoxP3 detected only in a subset of tumors." (PMID 41208884, 2025). "Specifically, IL-18 derived from CD4+ T cells or introduced exogenously has been shown to promote the proliferation and anti-tumor activity of CD8+ T cells and CAR-T cells." (PMID 40141358, 2025). "The outcomes illustrated that the reduction of CD4+ T and CD8+ T cells, or CD4/8+ T cells, weakened the inhibitory effect of TTN mutation on tumour growth post‐radiotherapy." (PMID 39748197, 2025). "CD4 + ICOS + PDCD1+ (PD-1) T-cells, resembling T follicular helper (Tfh) cells were more common in HPV+ve tumours, as were CD4 + naïve-like T-cell clusters and KIT + NK-cells." (PMID 39757146, 2025). "This approach reduced the tumor growth in MB49 mouse bladder cancer cells while enhancing the pro-inflammatory response with enriched CD4+ and CD8+ T cells." (PMID 40699676, 2025). "The administration of low‐dose metronomic CTX results in a reduction of Tregs in both the bloodstream and tumor sites, while concurrently increasing the numbers of CD4+ and CD8+ T cells." (PMID 40703615, 2025). "There was also decreased intratumoral infiltration and a distinct CD4+ T cell profile in oligo-synchronous BM, both in the tumor microenvironment and peripheral blood, compared to polymetastatic BM patients." (PMID 40346687, 2025). "In exploring the mechanisms of this allogeneic CD4+ T cell help in tumor challenge studies, we discovered that this help was induced only at an early stage of tumor growth by the peptide-pulsed MHC class II semiallogeneic DC vaccine." (PMID 40857404, 2025). "Instead of initiating an anti-tumor response, CD4 T cells are co-opted by H/RS cells to provide growth signals, promote immune suppression, and shield the tumor from cytotoxic effects." (PMID 41256864, 2025). "Recent studies highlight the role of CD4+ T cells in forming triads with DCs to enhance CD8+ T cell function during tumor eradication." (PMID 40606756, 2025). "Neutrophils presented the highest immune‐inhibitory scores among the tumor‐infiltrating immune cells, followed by macrophages and CD4+ T cells." (PMID 40433893, 2025). "Compared with cisplatin treatment, tumor-infiltrating CD4+, CD8+ T cells, and CD11c+ DCs in the lung tissues rose significantly in HS-Pt-CDs+690 nm treated groups with proportions of 1.8%, 8.8%, and 18.7%, respectively." (PMID 40234392, 2025).
tumor (continued). "B cells contribute by manufacturing antibodies targeted explicitly against tumor cells, while T-cells, particularly CD4 and CD8 subsets, orchestrate an anti-tumor response by interacting with cell surface markers." (PMID 40040878, 2025). "Tumor regulating B lymphocytes produce TGFb, which acts on monocyte and granulocyte subpopulations by suppressing antitumor CD4+ and CD8+ T cells." (PMID 40802351, 2025). "Conversely, CD4+ T cell depletion reduced tumor growth in B16F10-mock tumors, consistent with the findings of a previous report." (PMID 40243581, 2025). "In 2017, vaccines using personalized mRNA induced polyfunctional CD8+ and CD4+ T-cell responses in 24.8% and 48.0% of the vaccinated neoantigens and led to tumor regression or prolonged stable disease condition." (PMID 41514653, 2025). "Epstein-Barr virus (EBV) is known to modulate the tumor microenvironment by inducing immune cell infiltration and altering immune cell pathways, such as induction of plasma, CD4 and CD8 T-cells." (PMID 40028540, 2025). "Each trial highlights the use of different nanoparticle platforms designed to deliver specific tumor antigens or targets, aiming to enhance CD4+ T-cell activation and immune modulation." (PMID 40860882, 2025). "The precise mechanisms by which effector CD4+ T cells mediate tumor rejection remain incompletely defined." (PMID 40634636, 2025). "We established a 4T1 tumor‐bearing mice model and analyzed the proportions of CD4+ T and CD8+ T cells in the spleen using flow cytometry and immunohistochemistry." (PMID 40497373, 2025). "These statistical tests indicated that CD4-positive patients had a slight tendency to present tumor margin infiltration less frequently." (PMID 40362599, 2025). "In some cases, TIL cells are expanded as the mixed CD8+ and CD4+ T cell population derived directly from the primary tumor." (PMID 41479781, 2025). "Lymphocytes, particularly tumor‐infiltrating CD8+ T cells supported by CD4+ T cells (via IL‐2 and interferon‐gamma), are essential for anti‐tumor immunity." (PMID 41307215, 2025). "The number of CD8+ T cells was markedly more than that of CD4+ T cells in 60% (6/10) tumor samples, with a ratio of CD4/CD8 from 1:2 to 1:6." (PMID 40899568, 2025). "Subsequently, we examined the changes in the lymphoid subgroups using flow cell sorting before and after treatment and found that CD8+ and CD4+T cells were significantly increased, suggesting that these cells play critical roles in tumor cell eradication." (PMID 40670983, 2025). "For example, BATF overexpression in TILs attenuates TOX locus opening and TOX expression, and CD4+ T cell help in CD8+ T cell–dendritic cell–CD4+ T cell triads within a tumor prevents TOX locus opening and ameliorates CD8+ T cell exhaustion." (PMID 40746547, 2025). "Like MDSCs, TAMs also reduce the proliferation of anti-tumor cytotoxic T-cells while promoting regulatory CD4+ T-cell growth by expressing PD-L1 on their surface, secreting TGF-β and IL-10, and producing nitric oxide and arginase." (PMID 40869156, 2025). "Elevated kynurenine levels have been associated with immune suppression, as they reduce the activity of CD4+ T cells, which are crucial for the body’s anti-tumor response." (PMID 40927726, 2025). "Due to their pivotal roles in modulating the immune response, promoting tumor progression, and facilitating immune evasion across various cancer types, we also focused on soluble CD4 (sCD4), soluble CD73 (sCD73) and soluble CD74 (sCD74)." (PMID 39910579, 2025). "This leads to ZIKV-induced tumour clearance and long-term immunity against tumour cells in immunocompetent glioma mice models, which is dependent on CD4+ and CD8+ T cells." (PMID 40240536, 2025). "By Day 17, the proportion of CD4 + /CD8 + effector T cells significantly decreased in tumours treated with antibody." (PMID 39939955, 2025).